ADIPOR1 (adiponectin receptor 1)
Diseases named in the same sentence as ADIPOR1 in open-access papers (continued):
Sharing a sentence is not in itself a finding about the gene and the disease.
neuroblastoma (2 papers, 2021 to 2022). Neuroblastoma (NB) is the most common solid, extracranial childhood tumor. "Moreover, we have confirmed that osmotin action is mainly attributed to the activation of AdipoR1, as the silencing of AdipoR1 expression abolished the osmotin ability to activate p-AMPK and SIRT1 in SH-SY5Y neuroblastoma cells." (PMID 35204143, 2022).
nonalcoholic steatohepatitis (2 papers, 2013 to 2024). "Rosiglitazone treatment for 8 weeks improves the histological lesions in liver of nonalcoholic steatohepatitis rats, increases mRNA and protein expressions of AdipoR1 and AdipoR2 in liver and visceral fat, with down-regulation of the two receptors in muscle." (PMID 23349663, 2013).
Parkinson disease (2 papers, 2022 to 2023). A progressive degenerative disorder of the central nervous system characterized by loss of dopamine producing neurons in the substantia nigra and the presence of Lewy bodies in the substantia nigra and locus coeruleus. "This pathological event is the hallmark of neurodegenerative diseases, such as Parkinson’s, Alzheimer’s, or prion disease, which are also overrepresented as the top pathways enriched by the upregulated DEGs in rods of AdipoR1–/– mice." (PMID 35015730, 2022). "For instance, the ceramide C24:1 (d18:1/24:1), which we found as one of the top elevated ceramides in the retina and RPE of AdipoR1–/– mice, was also identified as one of the 2 (next to d18:0/24:1) most highly elevated lipids in the primary visual cortex of Parkinson’s disease patients." (PMID 35015730, 2022).
retinal (2 papers, 2021 to 2023). "Here, we demonstrated the influence of adiponectin receptor 1 (ADIPOR1) deficiency in retinal neurodegeneration using Adipor1 knockout (KO) mice." (PMID 33963174, 2021). "Moreover, Osada and coworkers demonstrated the impact of AdipoR1 deletion in the abnormal lipid metabolism in the retina, as well as retinal neurodegeneration, specifically utilizing AdipoR1 KO mice." (PMID 37371562, 2023).
Sepsis (2 papers, 2017 to 2025). Sepsis is defined as life-threatening organ dysfunction caused by a dysregulated host response to infection. "AdipoR1 played a crucial factor in inflammation process of HUVECs induced by LPS, and maybe the potential therapy for patients with sepsis." (PMID 29190778, 2017). "It is well known that AdipoR1 play the crucial effect on the process of inflammation, and maybe alternatively used as the possible therapeutic tactic for treatment on sepsis." (PMID 29190778, 2017).
adrenal tumors (1 paper, 2023). "In an analysis of 128 resected adrenal tumors, both AdipoR1 and AdipoR2 expression levels were significantly higher in ACC compared with benign adrenal tumors." (PMID 37297933, 2023).
advanced heart failure (1 paper, 2013). Patients with advanced heart failure have severe limitations, experiences symptoms even while at rest and are mostly bedbound patients. "However, patients with advanced heart failure present increased adiponectin with reduced expression of AdipoR1 and AdipoR2 as well as reduced activation of AMP kinase, a known downstream signaling molecule, suggesting a functional adiponectin resistance in advanced heart failure." (PMID 23843680, 2013).
allergic asthma (1 paper, 2021). A asthma with a basis in a pathological type I hypersensitivity reaction. "We previously showed that DIO mice under allergic asthma model showed a reduced frequency of Helios- AdipoR1+ Tregs in the lungs compared to DIO non-allergic mice." (PMID 34084174, 2021).
autosomal dominant retinitis pigmentosa (1 paper, 2017). Autosomal dominant retinitis pigmentosa (RP) is an autosomally dominant inherited retinal dystrophy leading to progressive loss of the photoreceptors and retinal pigment epithelium and resulting in blindness usually after several decades. "In human, a rare loss-of-function mutation in AdipoR1 causes autosomal dominant retinitis pigmentosa, which is likely due to AdipoR1 regulating fatty acid composition of the retina." (PMID 28886012, 2017).
calcification (1 paper, 2020). Process by which organic tissue becomes hardened by the physiologic deposit of calcium salts. "In renal allograft recipients, both CTRP9 and HMW-ADPN were suggested to prevent the progression of aortic calcification through AdipoR1." (PMID 31945100, 2020).
cardiac arrest (1 paper, 2023). Cessation of breathing and/or cardiac function. "Autophagy-mediated ADIPOR1-AMPK signaling can suppress apoptosis in brain cells induced by cardiac arrest or cardiopulmonary resuscitation." (PMID 38049739, 2023).
cartilage disease (1 paper, 2023). Softening and degeneration of the CARTILAGE. "Regarding bone and cartilage diseases, adiponectin and its receptors, adiponectin receptor 1 (adipoR1), adipoR2, and T-cadherin have been reported to be involved in inflammation and degeneration." (PMID 37239908, 2023).
chondrosarcoma (1 paper, 2015). A malignant cartilaginous matrix-producing mesenchymal neoplasm arising from the bone and soft tissue. "Previous report documented that human chondrosarcoma expressed AdipoR1 and AdipoR2 receptor isoforms." (PMID 26468982, 2015). "In addition, CM from chondrosarcoma cells demonstrated that AdipoR1 and AdipoR2 siRNA significantly reduced adiponectin-mediated migration and tube formation of EPCs." (PMID 26468982, 2015). "In addition, both AdipoR1 and AdipoR2 receptors involved in adiponectin-promoted metastasis in human chondrosarcoma." (PMID 26468982, 2015).
coronary stenosis (1 paper, 2012). Narrowing of the coronary artery lumen diameter. "The lack of collagen deposits in PS in absence of coronary stenosis and inflammation suggests the occurrence of non-ischemic ventricular remodeling due to mechanical stress, which could impair the cardiac ADN/AdipoR1 system." (PMID 23164042, 2012).
disc degeneration (1 paper, 2016). "Using a rat tail temporary static compression model, AdipoR1 and AdipoR2 expression were found to decrease according to disc degeneration severity." (PMID 27876065, 2016). "In the NP and AF, AdipoR1 and AdipoR2 expression gradually decreased with increased severity of disc degeneration." (PMID 27876065, 2016). "Expression levels of AdipoR1 and AdipoR2 in both the NP and AF were gradually decreased with increased disc degeneration." (PMID 27876065, 2016).
endocarditis (1 paper, 2017). Inflammation of the endocardium. "Genes expressed significantly lower in epididymal adipose tissue obtained from rats with endocarditis were the genes for the adiponectin receptor type 1 (AdipoR1) and phosphoenolpyruvate carboxykinase-1 (PEPCK-1)." (PMID 28428684, 2017).
endometriosis (1 paper, 2016). The growth of functional endometrial tissue in anatomic sites outside the uterine body. "Adiponectin can suppress endometriosis by inhibiting ESC proliferation and increased AdipoR1 and AdipoR2 expression." (PMID 26459399, 2016).
epididymitis (1 paper, 2023). Inflammation of the epididymis. "Rahmanifar and Tabandeh reported that ADIPOQ, ADIPOR1 and ADIPOR2 transcripts are present in the testes, epididymitis, and vesicular and bulbourethral glands." (PMID 36830390, 2023).
epilepsy (1 paper, 2022). A brain disorder characterized by episodes of abnormally increased neuronal discharge resulting in transient episodes of sensory or motor neurological dysfunction, or psychic dysfunction. "We found that ADIPOR1 and ADIPOR2, as cognate receptors of adiponectin, were highly expressed in the epilepsy group." (PMID 36138892, 2022).
esophageal cancer (1 paper, 2015). A primary or metastatic malignant neoplasm involving the esophagus. "ADIPOR1, expressed at high levels in skeletal muscle and pancreatic beta cells, is expressed in many types of cancer, including breast, colorectal, pancreatic, and esophageal cancers." (PMID 26047008, 2015).
gastric ulcer (1 paper, 2021). An ulcerated lesion in the mucosal surface of the stomach. "Our data suggest that AdipoR1 and AdipoR2 activation may be an attractive therapeutic strategy to inhibit development of gastric ulcers." (PMID 34063466, 2021).
heart failure (1 paper, 2020). Inability of the heart to pump blood at an adequate rate to meet tissue metabolic requirements. "While others state that the association of hyperadiponectinemia and increased mortality in heart failure was a phenomenon of ‘adiponectin resistance’, characterized by downregulation of AdipoR1 and phosphorylation of the downstream proteins like AMPK and P38MAPK." (PMID 32731857, 2020).
hematoma (1 paper, 2022). A hematoma is a collection of blood from a vascular structure into an extravascular space. "Accordingly, we demonstrate that APN promote phenotypic change of microglia from “classically” M1 activated to “alternatively activated” M2 states and enhances hematoma clearance, thereby reducing hydrocephalus by activation of PPARγ via AdipoR1 signaling." (PMID 35720361, 2022). "Thus, in this present study, we hypothesize that APN will attenuate neuroinflammation and accelerate hematoma clearance through the AdipoR1/AMPK signaling pathway after GMH via regulation of M1/M2 polarization." (PMID 35720361, 2022). "AdipoR1-mediated activation of the APPL1/LKB1/AMPK/PPARγ pathway had a critical role in the M1 to M2 transformation, as well as in the process of hematoma resolution." (PMID 35720361, 2022).
hemorrhage (1 paper, 2022). Loss of blood from the vascular compartment to the exterior or into nonvascular body space as a result of rupture or severance of the blood vessels. "In all, we propose that APN works as a potential therapeutic agent to ameliorate the inflammatory response following GMH by enhancing the M2 polarization of microglia via AdipoR1/APPL1/AMPK/PPARγ signaling pathway, ultimately attenuating inflammatory brain injury induced by hemorrhage." (PMID 35720361, 2022).
hyperopia (1 paper, 2022). A refractive error in which rays of light entering the eye parallel to the optic axis are brought to a focus behind the retina, as a result of the eyeball being too short from front to back. "Our measurement of refractive error using an infrared photorefractor also confirmed significant changes (p-value < 0.0001) in refraction at 10 weeks of age, when the refractive errors of both Adipor1 tm1Dgen and Mfrprd6 homozygotes shifted towards hyperopia." (PMID 35163536, 2022).
hypertrophic cardiomyopathy (1 paper, 2025). A condition in which the myocardium is hypertrophied without an obvious cause. "For example, patients expressing an AdipoR1 mutation demonstrate hypertrophic cardiomyopathy, whereas the overexpression of mutant AdipoR1 in cultured cardiomyocytes or the expression of the mutant receptor in transgenic mice leads to hypertrophic responses in the absence of any other intervention." (PMID 41515891, 2025).
influenza (1 paper, 2024). An acute viral infection of the respiratory tract, occurring in isolated cases, in epidemics, or in pandemics; it is caused by serologically different strains of viruses (influenzaviruses) designated A, B, and C, has a 3-day incubation period, and usually lasts for 3 to 10 days. "in influenza-infected AdipoR1 and 2 knockout mice, found that only AdipoR1-/- aged mice exhibited less severe symptoms of infection after influenza infection." (PMID 39840070, 2024).
insulinoma (1 paper, 2018). "AdipoR1 protein expression and localization in islets from AdipoR1 mice as well as in an AdipoR1-transfected mouse insulinoma cell line were confirmed, as was the activation of both AMPK and Akt in AdipoR1 mice by adiponectin." (PMID 29304075, 2018).
late-onset retinal degeneration (1 paper, 2022). Late-onset retinal degeneration is an inherited retinal dystrophy characterized by delayed dark adaptation and nyctalopia and drusen deposits presenting in adulthood, followed by cone and rod degeneration that presents in the sixth decade of life, which leads to central vision loss. "Moreover, a recent study suggests a role for Adipor1 in the pathogenesis of Late-Onset Retinal Degeneration (L-ORD)." (PMID 35873810, 2022).
leukemia (1 paper, 2025). A malignant (clonal) hematologic disorder, involving hematopoietic stem cells and characterized by the presence of primitive or atypical myeloid or lymphoid cells in the bone marrow and the blood. "The lack of a significant effect following AdipoR2 silencing further confirms that AdipoRon primarily acts via AdipoR1 to regulate angiogenesis in leukemia cells." (PMID 41217652, 2025). "Finally, we aimed to determine whether AdipoRon’s effects on angiogenesis in leukemia are mediated by AdipoR1 and/or AdipoR2." (PMID 41217652, 2025). "Finally, silencing of AdipoR1, but not AdipoR2, diminishes the AdipoRon-induced upregulation of the angiogenesis-related factors, suggesting that AdipoR1 is the primary receptor mediating the effects of adiponectin in leukemia cells." (PMID 41217652, 2025).
Lymphatic Metastasis (1 paper, 2011). Transfer of a neoplasm from its primary site to lymph nodes or to distant parts of the body by way of the lymphatic system. "In addition, negative AdipoR1 immunostaining was significantly higher in patients with lymphatic metastasis (p = 0.013) and peritoneal dissemination (p = 0.042)." (PMID 22078265, 2011).
male infertility (1 paper, 2024). The inability of the male to effect fertilization of an ovum after a specified period of unprotected intercourse. "Moreover, we demonstrated that decreased AMPK activity and increased caspase-6 activity in the testis from AdipoR1 KO mice and that AdipoR1 KO mice were associated with male infertility due to smaller testis, lower sperm counts and lower sperm motility." (PMID 38459078, 2024). "This was the first study to demonstrate that decreased AdipoR1/AMPK signaling led to increased caspase-6 activity/increased apoptosis in the testis thus likely accounting for male infertility." (PMID 38459078, 2024). "Our study showed that decreased adiponectin/AdipoR1 signaling accounts for male infertility as it involves apoptosis via the AMPK-caspase-6 axis." (PMID 38459078, 2024).
metastatic cancers (1 paper, 2023). A carcinoma which has spread from the original site of growth to another anatomic site. "Moreover, the adiponentin–adiponectin receptor 1 (AdipoR1) axis may serve as a predictor of tyrosine kinase inhibitor response and could be a potential therapeutic target in the future treatment of metastatic cancers." (PMID 37444627, 2023).
microphthalmia (1 paper, 2025). Congenital or developmental anomaly in which the eyeballs are abnormally small. "We conclude that, in mice, Mfrp, Prss56, and Adipor1 mutations yield similar microphthalmia phenotypes involving both the anterior and posterior eye." (PMID 40154727, 2025).
mucinous carcinomas (1 paper, 2016). "We found a trend towards higher expression of all these markers except for Rage, in the subgroup of mucinous carcinomas which, although of borderline significance, seemed to be more prominent for AdipoR1 and AGE." (PMID 26931562, 2016). "There was a trend towards higher expression of all markers (except for RAGE) in the subgroup of mucinous carcinomas which, although of borderline significance, seemed to be more prominent for AdipoR1 and AGE." (PMID 26931562, 2016).
nasopharyngeal carcinoma (1 paper, 2022). A carcinoma arising from the nasopharyngeal epithelium. "We further determined if boosting the activity of both adiponectin receptors, AdipoR1 and AdipoR2, will stall the growth of nasopharyngeal carcinoma, if so, what is the impact of altering AdipoRs signaling on cell cycle progression of NPC cells." (PMID 35164782, 2022).
non-small cell lung carcinoma (1 paper, 2016). A group of at least three distinct histological types of lung cancer, including non-small cell squamous cell carcinoma, adenocarcinoma, and large cell carcinoma. "A study of non-small cell lung cancer also indicates that patients with higher expression of AdipoR1 have longer overall survival and AdipoR2 expression is inversely correlated with tumor size." (PMID 27119501, 2016).
Osteopenia (1 paper, 2019). Osteopenia is a term to define bone density that is not normal but also not as low as osteoporosis. "We found that in AIS osteopenia, high plasma adiponectin levels which may due to the gene variation may affect bone mass through the modulation of RANKL/OPG in osteoblasts and IL6 release in chondrocytes by binding to adipoR1." (PMID 30819183, 2019).
osteosarcoma (1 paper, 2020). A usually aggressive malignant bone-forming mesenchymal neoplasm, predominantly affecting adolescents and young adults. "In detail, we detected in Saos-2 and U2OS human osteosarcoma cell lines mRNA and protein expression levels of both canonical adiponectin receptors (ADIPOR1 and ADIPOR2) and noncanonical adiponectin receptor (CAD13)." (PMID 32411241, 2020).
papillary thyroid carcinoma (1 paper, 2021). "Indeed, Mitsiades reported that tissues and cell lines derived from human papillary thyroid carcinoma expressed Acrp30 receptors (AdipoR1 and AdipoR2)." (PMID 33587254, 2021).
peritonitis (1 paper, 2017). Inflammation of the peritoneum (tissue that lines the abdominal wall and covers most of the organs in the abdomen). "Gene expression profiles were similar between epididymal and subcutaneous adipose tissue depots in the mouse peritonitis model (PYCARD, IL-6, adiponectin, AdipoR1, visfatin, and LOX-1)." (PMID 28428684, 2017).
renal tumor (1 paper, 2019). "We found a decrease in the expression of AdipoR1 in renal tumor cell lines ACHN and Caki-1 (from metastatic site) incubated with hRAT-CMs." (PMID 31534630, 2019).
scleroderma (1 paper, 2012). Scleroderma is a rare autoimmune connective tissue disorder characterized by abnormal hardening of the skin and, sometimes, other organs. "The results showed approximately 40% lower levels of AdipoR1 mRNA in scleroderma fibroblasts compared to normal fibroblasts, but the differences were not statistically significant (P = 0.22)." (PMID 23092446, 2012). "The expression of adiponectin receptor 1 was selectively reduced in skin biopsies from patients with scleroderma." (PMID 23092446, 2012).
Stroke (1 paper, 2015). Sudden impairment of blood flow to a part of the brain due to occlusion or rupture of an artery to the brain. "Moreover, we also proved that electroacupuncture alleviated cerebral ischemic injury in diabetic mice stroke model through adiponectin/AdipoR1-mediated signaling pathway, in which glycogen synthase kinase 3-β might be one crucial molecule in the downstream pathway of AdipoR144." (PMID 26611106, 2015).
syndromic retinitis pigmentosa (1 paper, 2022). A retinitis pigmentosa that is part of a larger syndrome. "Mutations of the ADIPOR1 gene have been associated with nonsyndromic and syndromic retinitis pigmentosa." (PMID 35015730, 2022).
trigeminal neuralgia (1 paper, 2023). Trigeminal neuralgia is a nerve disorder that causes a stabbing or electric-shock-like pain in parts of the face. "In a trigeminal neuralgia model induced by chronic constriction injury of infraorbital nerve, blockade of adipoR1 signaling suppressed mechanical allodynia, which was prevented by silencing Cav3.2." (PMID 37620777, 2023). "Knowledge of the adipoR1-mediated CK2α-PKCβ1-Cav3.2 cascade in peripheral sensory neurons may pave the way for developing potential therapeutic targets in clinical treatment of pain disorders such as trigeminal neuralgia." (PMID 37620777, 2023).
triple-negative breast carcinoma (1 paper, 2019). An invasive breast carcinoma which is negative for expression of estrogen receptor (ER), progesterone receptor (PR), and human epidermal growth factor receptor 2 (HER2). "Given the importance of SET1B-ADIPOR1 signaling in triple negative breast cancer (TNBC), AdipoRon, the ADIPOR1 agonist, has been proposed as a novel therapeutic strategy for clinical treatment of TNBC." (PMID 31747960, 2019).